REN (renin)
Diseases named in the same sentence as REN in open-access papers (continued):
Sharing a sentence is not in itself a finding about the gene and the disease.
acute kidney injury (continued). "Furthermore, renal failure can accelerate CAD by the renin–angiotensin–aldosterone system (RAAS), pre-calcification pathway, advanced glycation end-products (sRAGE), and intestinal microbiome and IR, promoting the progression of coronary atherosclerosis or acute cardiovascular events." (PMID 41295353, 2025). "The mechanisms underlying acute renocardiac syndrome are not clearly understood, but may involve direct (e.g., cytokines, sympathetic tonus and renin–angiotensin–aldosterone system) or indirect (e.g., fluid and electrolyte imbalances) effects of acute kidney injury on the heart." (PMID 26395899, 2015). "Major surgery frequently triggers acute kidney injury (AKI), leading to adverse physiological responses, including fluid imbalance, renin-angiotensin-aldosterone pathway activation, inflammatory mediator release, and metabolic disruption." (PMID 41285121, 2025). "Acute kidney injury was reported in GLP-1 RA trials and was believed to be secondary to volume contraction due to GI symptoms or concomitant use of drugs working on the renin–angiotensin pathway." (PMID 38730578, 2024). "This is accompanied by diuretic resistance, activation of the renin-angiotensin-aldosterone system (RAAS), impairment of renal function, and even the occurrence of acute kidney injury (AKI)." (PMID 36698930, 2022). "Renovascular hypertension induced by 2 Kidney-1 Clip (2K-1C) is a renin-angiotensin-system (RAS)-dependent model, leading to renal vascular rarefaction and renal failure." (PMID 24223811, 2013). "Renovascular hypertension induced by 2 Kidney-1 Clip (2K-1C) is a renin-angiotensin-system (RAS)-dependent model, leading to intrarenal vascular rarefaction and renal failure." (PMID 24223811, 2013). "Although the temporary discontinuation of renin–angiotensin system (RAS) inhibitors before contrast exposure is a common clinical practice, meta-analytic evidence indicates that such withdrawal does not consistently reduce the risk of contrast-associated acute kidney injury (CA-AKI)." (PMID 41300867, 2025). "Triple Whammy (TW) therapy, a combination of renin-angiotensin system inhibitors (RASIs), diuretics, and non-steroidal anti-inflammatory drugs (NSAIDs), is associated with an increased risk of acute kidney injury (AKI)." (PMID 40826437, 2025). "Combining the renin inhibitor aliskiren with an ACEI or ARB significantly increased the risk of hyperkalemia and did not reduce the risk of cardiovascular disease or renal failure." (PMID 38332893, 2024). "However, in CKD, activating the renin–angiotensin–aldosterone system impairs NO formation and stimulates NADPH oxidase (NOX), promoting renal failure." (PMID 38773318, 2024). "However, these benefits are offset by risks, including an increased likelihood of adverse effects such as acute kidney injury (AKI) and cardiovascular events in diabetic populations, especially when combined with other medications like renin–angiotensin–aldosterone system blockers." (PMID 40866832, 2025). "Hepatorenal syndrome-acute kidney injury (HRS-AKI, formerly Type 1 HRS) is driven by peripheral arterial vasodilation and cardiac dysfunction, which leads to reduced effective arterial volume and activation of the renin-angiotensin-aldosterone system and sympathetic nervous system." (PMID 39194320, 2024). "Diabetic patients who are treated with renin–angiotensin system blockers and develop volume depletion and/or are given a nonsteroidal anti-inflammatory drug can quickly develop acute kidney injury, precipitating severe lactic acidosis in the setting of metformin therapy." (PMID 37993970, 2023). "However, low renin renovascular HTN has also been reported previously, which may be attributed to renal ischemia, renal failure, or underestimation of renin levels because of technical problems and/or drug interference." (PMID 35310978, 2022).
acute kidney injury (continued). "AKI: Acute kidney injury; CRS: Cardio-renal syndrome; EV: Extracellular vesicle; RAAS: Renin-angiotensin-aldosterone system; TNF: Tumour necrosis factor." (PMID 24451176, 2014). "The severity of acute renal failure and oliguria therefore may be a product of tubular toxicity, tubular obstruction, dehydration and compounding factors such as the use of diuretics, non-steroidal anti-inflammatory agents and renin-angiotensin system blockade." (PMID 19068112, 2008).
essential hypertension (108 papers, 2005 to 2026). Hypertension that presents without an identifiable cause. "Our results among children and adolescents with primary hypertension indicate that the concentration of active renin is positively associated with blood pressure elevation and serum potassium level." (PMID 35627493, 2022). "Primary hypertension has also been associated with renin, an acid proteinase generated from the inactive precursor prorenin by the action of kallikrein." (PMID 19865517, 2009). "The developed model reveals: long-term control of arterial blood pressure is primarily through the baroreflex arc and the renin-angiotensin system; and arterial stiffening provides a sufficient explanation for the etiology of primary hypertension associated with ageing." (PMID 24555102, 2013). "The gene was identified in a subgroup with an undefined renin, salt-sensitive, subintermediate phenotype of primary hypertension." (PMID 40004206, 2025). "Contraction and relaxation of vascular smooth muscle play a significant role in primary hypertension, involving the nitric oxide-soluble guanylate cyclase-cyclic guanosine monophosphate pathway and the renin-angiotensin-aldosterone system." (PMID 38928382, 2024). "Here we explore if eGCSS relates to plasma renin and other clinical and biochemical characteristics in a cohort of patients with primary hypertension." (PMID 35414109, 2023). "Despite significant advances in knowledge regarding the pathogenesis of primary hypertension, the renin-angiotensin-aldosterone system remains at the heart of various pathophysiological concepts." (PMID 35627493, 2022). "In a classic Japanese study in patients with primary hypertension remaining on a high-sodium diet, the addition of potassium chloride resulted in a reduction in blood pressure but also in an increase in plasma renin activity." (PMID 35627493, 2022). "Our cross-sectional study evaluated active renin concentrations in a large population of pediatric patients with primary hypertension and compared it with healthy peers." (PMID 35627493, 2022). "The aldosterone–renin ratio of PA patients was much higher than that of primary hypertension patients (426.2 vs. 6.1, p < 0.001)." (PMID 34484110, 2021). "ARA is related to higher blood pressure and higher direct renin concentration in middle-aged patients with primary hypertension, and these patients deserve stricter blood pressure control." (PMID 32328302, 2020). "In conclusion, we confirmed that ARA contributed to higher blood pressure in patients with primary hypertension through excessive renin and activation of the renin-angiotensin system." (PMID 32328302, 2020). "Our study aimed to assess active renin concentration in children with primary hypertension." (PMID 35627493, 2022). "Second, the renin-angiotensin system might be considered as another modulator for NGF production in primary hypertension." (PMID 35284140, 2022). "In the present study, we observed the association between ARA and clinical characteristics among middle-aged patients with primary hypertension who underwent complete pharmacological wash-out to elimination the influence of the medicines on the sympathetic nerve system and renin-angiotensin system." (PMID 32328302, 2020). "The purpose of the present study, therefore, was to examine if eGCSS relates to plasma renin (used as a surrogate marker of sodium retention/volume expansion) and albumin/creatine ratio (as a sensitive measure of target organ damage) in a cohort of patients with primary hypertension." (PMID 35414109, 2023). "Thus, we evaluated active renin concentration, clinical parameters, office and ambulatory blood pressure, and biochemical parameters in 51 untreated adolescents with primary hypertension (median: 14.4 [interquartile range—IQR: 13.8–16.8] years) and 45 healthy adolescents." (PMID 35627493, 2022).
essential hypertension (continued). "The renin-angiotensin-aldosterone system plays an extremely important in the pathogenesis of primary hypertension, and NO is an important vasodilator factor in the body, and their expression changes in serum can reflect the development trend of primary hypertension." (PMID 36046450, 2022).
hyperuricemia (106 papers, 2011 to 2026). An abnormally high level of uric acid. "In ADTKD-REN, heterozygous REN mutations cause decreased renin synthesis, clinically presenting with hypotension, hyporeninemic hypoaldosteronism, anemia, and early-onset hyperuricemia." (PMID 41480152, 2025). "There are three main associations between hyperuricemia and renal damage, including uric acid crystals, increased blood pressure via the renin–angiotensin system, and increased concentrations of intracellular uric acid." (PMID 40839334, 2025). "Plasma renin activity and plasma aldosterone concentration were also elevated in rats with hyperuricemia, but these associations were unclear in adults with essential hypertension." (PMID 36431026, 2022). "Hyperuricemia is linked to impaired production of nitric oxide the activation of renin-angiotensin system." (PMID 35459096, 2022). "Hyperuricemia accelerates renal progression by increasing renal renin and cyclooxygenase-2 expression and causing vascular smooth muscle cell proliferation." (PMID 34063419, 2021). "In summary, we describe a novel dominant mutation in the REN gene in an individual with long-standing anaemia, hyperuricaemia and slowly progressive CKD." (PMID 28701203, 2017). "For example, an oxonic acid diet in rats is known to cause hyperuricemia through elevated plasma renin activity." (PMID 28979210, 2017). "Other than the uric acid crystal effect, hyperuricemia has been reported to cause an afferent renal arteriopathy and tubulointerstitial fibrosis in the kidney by activating the renin–angiotensin–aldosterone system." (PMID 25064611, 2014). "Hyperuricemia can lead to the formation of urate crystals in the kidneys, causing inflammation and injury to the renal tissues and also by activation of the intrarenal renin-angiotensin system." (PMID 37701002, 2023). "Experimental studies of serum and intracellular hyperuricemic models have found that hyperuricemia causes renal arterionephrosclerosis/arteriolopathy owing to the activation of the renin–angiotensin–aldosterone system and decreased nitric oxide bioavailability." (PMID 35260678, 2022). "Our study found for the first time that some antihypertensive drugs with central action (clonidine), α and β blockers (carvedilol and labetalol), renin inhibitors (aliskiren), and vasodilators (hydralazine and nitroglycerin) were associated with increased risk of hyperuricaemia, gout or related AEs." (PMID 36699079, 2022). "Moreover, hyperuricemia downregulates the production of NO (nitric oxide) in endothelial cells, this, in association with the activation of the renin‐angiotensin‐aldosterone (RAA) system by high UA levels." (PMID 35748644, 2022). "The association of hyperuricemia with increased cardiovascular risk may partly be explained by the activation of the renin-angiotensin system (RAS)." (PMID 36431026, 2022). "In addition, hyperuricemia-associated activation of the renin-angiotensin system promoted vascular intima proliferation, causing hypoperfusion of the renal tubules, and induced renal inflammation and fibrosis, contributing to HN." (PMID 32116724, 2020). "Furthermore, hyperuricemia may activate the renin-angiotensin system, cause glomerular hypertension, and reduce perfusion, which ultimately led to the formation of glomerular sclerosis." (PMID 33194389, 2020). "Hyperuricemia activates the renin–angiotensin system and inhibits endothelial nitric oxide production, all contributing to vascular injury." (PMID 41497488, 2025). "Hyperuricemia stimulates the renin–angiotensin system through inducing renal vasoconstriction and increasing blood pressure, which result in a vicious circle leading to the progression of renal disease." (PMID 38586465, 2024). "The presumed mechanism by which hyperuricemia contributes to CVD involves renin-angiotensin system activation, IR, inflammatory reaction, and oxidative stress." (PMID 38831965, 2024).
hyperuricemia (continued). "Elevated serum uric acid levels heighten the risk of cardiovascular disease (CVD) mortality, potentially due to mechanisms by which hyperuricemia activates the renin-angiotensin system and induces hypertension." (PMID 39191722, 2024). "When mild hyperuricemia was induced in rats by providing oxonic acid in the diet, blood pressure was elevated, and juxtaglomerular renin expression increased." (PMID 36431026, 2022). "Hyperuricemia suppresses the production of nitric oxide, leading to activation of the renin-angiotensin system, which ultimately leads to endothelial damage." (PMID 35192651, 2022). "Hyperuricemia increases renin expression in glomerular cells and (pro)renin receptor expression in endothelial cells, while decreasing nitric oxide synthase-1 expression in the macula." (PMID 35909538, 2022). "Although recent advances in clinical and basic AD research have uncovered the important role of the renin–angiotensin–aldosterone system in the development of AD21–23, the precise mechanism by which hyperuricemia causes AD is yet to be fully elucidated." (PMID 32868835, 2020). "In hyperuricemia, the renin-angiotensin system in the kidney was activated, hyalinosis or narrowing of the arteriole was prominent in consecutive renal biopsy specimens, and the resistance index of the afferent artery was higher." (PMID 32716977, 2020). "Experimentally induced hyperuricemia was shown to be related to the inhibition of nitric oxide production, which activated the renin-angiotensin system and subsequently resulted in endothelial impairment." (PMID 31388342, 2019). "Heterozygous mutations in the gene encoding renin (REN) cause autosomal dominant tubulointerstitial kidney disease (ADTKD), early-onset anaemia and hyperuricaemia; only four different mutations have been described in the published literature to date." (PMID 28701203, 2017). "Another postulated mechanism is that hyperuricemia stimulates the renin-angiotensin system and proliferation of vascular smooth muscle cells (VSMCs)." (PMID 25048744, 2014). "Hyperuricemia may acutely influence blood pressure through a renin-dependent pathophysiological mechanism." (PMID 39191722, 2024). "Hyperuricemia could activate the renin-angiotensin- aldosterone system and further ventricular remodeling in HF that eventually leading to poor prognosis." (PMID 38172681, 2024). "Studies of the pathophysiology of heat stress-related CKD have identified several plausible mechanisms, including elevated renin-angiotensin-aldosterone system, renal sympathetic activity, rhabdomyolysis-induced hyperuricemia, and fructokinase-mediated hyperuricemia." (PMID 38106601, 2023). "In addition, hyperuricemia stimulated the vascular renin–angiotensin system, resulting in the excessive production of reactive oxygen species (ROS)." (PMID 36814289, 2023). "In addition, hyperuricemia is thought to activate the renin-angiotensin system and produce inflammatory mediators." (PMID 37238926, 2023). "While our study design did not include collection of these variables, it is important to note that hyperuricemia may lead to increased renin activity in some hypertensive individuals." (PMID 38001956, 2023). "Hyperuricemia may also lead to microvascular injury by stimulating the renin-angiotensin system (RAS), inhibiting endothelial-type nitric oxide and vascular smooth muscle proliferative effects." (PMID 35909538, 2022). "Specifically, significantly larger glomeruli were observed in children living in high-altitude environments compared with those of children living in plain areas, which may be related to hyperuricemia and activation of renin–angiotensin." (PMID 36297415, 2022). "Hyperuricemia may activate the renin-angiotensin system (RAS), inhibit NO release, and lead to an increase in systemic vascular resistance." (PMID 35856157, 2022).